LAD1 (ladinin 1)
Diseases named in the same sentence as LAD1 in open-access papers (continued):
Sharing a sentence is not in itself a finding about the gene and the disease.
cancer (continued). "Ladinin-1 (LAD1), an anchoring filament protein, has been associated with several cancer types, including cancers of the colon, lungs, and breast." (PMID 37718450, 2023). "As for the appearance of cancer cells, known as cancer grades, LAD1 protein levels were also significantly higher in all the cancer grades than in the normal tissue (p-value < 0.001)." (PMID 36613882, 2022). "Collectively, the reported literature suggests that the role of LAD1 in the aggressive progression of various cancers is accompanied by the upregulation of LAD1." (PMID 36613882, 2022). "Although these previous studies highlight the role of LAD1 in the progression of different cancers, the expression pattern and the prognostic value of LAD1 in PCa patients remains to be elucidated." (PMID 34516317, 2021). "Based on TCGA database, we found that the expression pattern of LAD1 was different in different cancers." (PMID 33536022, 2021). "Collectively, these studies demonstrate that aggressive progression of various cancers is accompanied by upregulation of LAD1 expression." (PMID 33267790, 2020). "Given that LAD1 was identified as a cancer cell-specific marker, we investigated whether its expression levels influenced gene expression, biological processes, and pathways within the cancer cell subgroup." (PMID 41423496, 2025). "FBLN5 was notably upregulated in fibroblasts, and LAD1 was markedly upregulated in cancer cells." (PMID 37325048, 2023). "LAD1 has been reported as being abundant in various cancers, including LUAD." (PMID 36613882, 2022). "Alternatively, based on its cellular localization, we hypothesize that LAD1 may modulate the reorganization of the cytoskeleton possibly through interaction with actin filaments and thus promote the invasive movement of cancer cells." (PMID 33267790, 2020). "Comparing immune cell response steps between the LAD1 high and low groups, we found significant upregulation in the release of cancer cell antigens, cancer antigen presentation, and priming and activation, while recognition of cancer cells by T cells was significantly downregulated by LAD1." (PMID 41423496, 2025). "Moreover, we conducted gene ontology (GO) analysis on the DEGs between cancer cells with high and low LAD1 expression, revealing the promotion of processes related to cell-cell junctions, cell-substrate junctions, and protein localization, while immune and vesicle-related processes were repressed." (PMID 41423496, 2025). "LAD1 expression was higher in patients with early-stage cancer compared to late-stage cancer (stage I+II—median: 11.10 [EU], range: 0.86–592.70 [EU]; stage III+IV—median: 8.55 [EU], range: 1.77–268.90 [EU]), though no statistical significance could be shown (p = ns)." (PMID 35008210, 2021). "However, how LAD1 promotes the migration and invasion of cancer cells remains obscure." (PMID 33267790, 2020). "Nevertheless, the molecular function of LAD1 in the progression of these cancers remains unclear." (PMID 33267790, 2020). "In order to further verify the high expression of LAD1 in LUAD tissues, immunohistochemical staining was performed on cancer tissues and corresponding adjacent tissues collected from 36 LUAD patients." (PMID 41423496, 2025). "Considering the specific expression of LAD1 in LUAD cancer cells, we further explored its expression profiles across various tissues and cancers." (PMID 41423496, 2025). "The role of LAD1 in cancer progression was validated by the A549 and CL1-0 LUAD cancer cell lines transfected with control siRNA or LAD1 siRNA with effective knockdown." (PMID 36613882, 2022). "The finding that LAD1 depletion resulted in more significant defects in invasion rather than migration suggests that the function of LAD1 may be more intimately associated with the invasive capability of cancer cells, such as the degradation of extracellular matrix by diverse proteases." (PMID 33267790, 2020).
cancer (continued). "In Caco-2 cells, LAD1 KD slightly reduced the mRNA expression of integrins such as ITGA2, ITGB1, and ITGA6, which are involved in cancer cell motility." (PMID 33267790, 2020). "Previous studies have reported that LAD1, C1ORF106, PVRL4, and KCNK5 are upregulated in cancer cells." (PMID 31164716, 2020). "Furthermore, we collected cancer tissue and corresponding adjacent tissue samples from 36 LUAD patients, used immunohistochemical staining to detect LAD1 expression, and analyzed its correlation with clinicopathological characteristics." (PMID 41423496, 2025). "We investigated the expression changes of LAD1 in various cancer types compared to their corresponding normal tissues." (PMID 41423496, 2025). "These genes included AGR2, KRT17, SPDEF, and LAD1 which were expressed in EV-RNA of patients 5 and 15 and of all cancer cell lines, but not in HBDs." (PMID 33761899, 2021). "Considering these results, we speculate that LAD1 is unlikely to be involved in gene expression for cancer cell motility." (PMID 33267790, 2020). "In addition, LAD1-depleted cells displayed no prominent alteration in the expression of integrins that modulate signaling pathways in cancer cells." (PMID 33267790, 2020). "Indeed, they include also LAD1 and BCL9, known to be involved in cancer invasiveness." (PMID 29017520, 2017). "Two of them, Ladinin-1 and the SARG protein, both related to cancer formation, are commonly found in non-infected and infected host cell eluates, while twenty-two proteins are identified in infected HCT-8 eluates only." (PMID 38473953, 2024).
infection (1 paper, 2022). The state of being infected such as from the introduction of a foreign agent such as serum, vaccine, antigenic substance or organism. "LAD1 is a disorder that involves deficiencies in three-membrane integrins, which prevents neutrophils from adhering to vessel walls at sites of infection." (PMID 35329073, 2022).
LAD1 also shares sentences with these, for which no sentence is quoted: immunodeficiencies (2 papers); acatalasia (1); ataxia telangiectasia (1); autosomal recessive chronic granulomatous disease (1); bacterial infections (1); Chediak-Higashi syndrome (1); cherubism (1); chronic granulomatous disease (1); clear cell renal cell cancer (1); Coffin-Lowry syndrome (1); colon cancer (1); congenital adrenal hyperplasia (1); Cyclic neutropenia (1); diabetes (1); Down syndrome (1); dysplasia (1); epidermodysplasia verruciformis (1); erythromelalgia (1); Glanzmann thrombasthenia (1); head and neck squamous cell carcinoma (1); hypophosphatasia (1); Langerhans cell histiocytosis (1); large cell lung cancer (1); laryngeal carcinoma (1); Leukocyte adhesion deficiency type I (1); Leukocyte adhesion deficiency type III (1); leukocytosis (1); lung squamous cell carcinoma (1); lymphoid neoplasm (1); mast cell sarcoma (1).
A further 2 diseases each share a sentence with LAD1 in 1 paper.